INO80 (INO80 complex ATPase subunit)
Diseases named in the same sentence as INO80 in open-access papers (continued):
Sharing a sentence is not in itself a finding about the gene and the disease.
cancer (27 papers, 2015 to 2025). A tumor composed of atypical neoplastic, often pleomorphic cells that invade other tissues. "For example, mutations in the SWI/SNF complexes occur in >20% of all human cancers, and INO80-complex mutations have also been identified in various cancers." (PMID 40877226, 2025). "INO80 complex aberrations are associated with cancer progression, as their binding to enhancers is crucial in mediating oncogenic gene expression." (PMID 41278204, 2025). "Strikingly, R-loop mutation burden was significantly higher in tumors holding SMARCA4, SMARCA5 and INO80 gene deficiencies, consistent with a direct role of these activities preventing R-loop mutagenesis in cancer." (PMID 37898641, 2023). "The ATP-dependent chromatin remodeling complex INO80 plays a pivotal role in resolving R-loops linked to DNA damage during replication in cancer cells." (PMID 37894353, 2023). "Here the authors reveal that the ATP-dependent chromatin remodelling INO80 complex promotes resolution of R-loops to prevent replication associated DNA damage in cancer cells." (PMID 32913330, 2020). "Here we show that the ATP-dependent chromatin remodelling INO80 complex promotes resolution of R-loops to prevent replication-associated DNA damage in cancer cells." (PMID 32913330, 2020). "Mechanistically, INO80 occupies enhancers near cancer-associated genes and promotes their expression, thus enhancing tumorigenicity." (PMID 31769422, 2019). "As both TORC1 and INO80 are conserved from yeast to humans, we investigated overlapping mutational signatures in cancer patient datasets." (PMID 29462149, 2018). "The data presented in this and other studies have revealed that INO80 deficiency results in a diversity of cancer phenotypes." (PMID 29383140, 2017). "However, further studies are needed to elucidate the association between INO80-mediated chromatin remodeling and miR-372 expression in cancer cells." (PMID 37445863, 2023). "Despite being a potential target in many cancers, inhibition of INO80 complex subunits is poorly investigated." (PMID 41278204, 2025). "In summary, the results of this paper provide a theoretical basis for elucidating the mechanism of action of the INO80 chromatin complex and provide new ideas for the development of subsequent cancer therapeutics." (PMID 37445863, 2023). "The INO80 complex has been confirmed to promote the resolution of R-loops and thus prevents replication-induced DNA damage in cancer cells." (PMID 36361605, 2022). "Although many genetic atlases in the INO80 and SWR1 family locus have been revealed in cancer, it remains a contentious issue to study the underlying regulatory mechanisms." (PMID 36361605, 2022). "Our study supports the idea that INO80 defines a pathway for the removal of R-loop structures from chromatin that is critical for maintenance of genome integrity and cancer cell proliferation." (PMID 32913330, 2020). "Our work suggests that INO80-dependent resolution of R-loops promotes DNA replication in the presence of transcription, thus enabling unlimited proliferation in cancers." (PMID 32913330, 2020). "Taken together, our results suggest that R-loop resolution facilitated by INO80 ameliorates DNA damage at sites of transcription-replication conflicts to promote cancer cell proliferation and prevent cell death." (PMID 32913330, 2020). "Our results suggest that R-loop resolution driven by INO80 prevents genotoxic collisions between transcription and replication, enabling unlimited proliferation of cancer cells." (PMID 32913330, 2020). "Depletion of INO80 in cancer cells decreases oncogenic transcription, compromises cell proliferation and subsequent tumour growth." (PMID 32913330, 2020). "INO80 is upregulated in cancer cell lines and human cancer tissues, including lung cancer, colon cancer, and melanoma." (PMID 31769422, 2019). "Although the alteration frequency of INO80 subunits is high in multiple cancers, including PDAC, only a few studies have been done." (PMID 31769422, 2019).
cancer (continued). "Functional studies demonstrated that INO80 is required for proliferation, viability, clonogenicity, and anchorage-independent growth of cancer cells in vitro and tumor formation in vivo." (PMID 31769422, 2019). "The majority of the studies focusing on the INO80 complex in cancer have been performed by using INO80 knockdowns." (PMID 31769422, 2019). "We found that INO80 subunits have a high frequency of gaining copy numbers and a high rate of amplification in many cancer types." (PMID 29383140, 2017). "Further studies that explore additional cancer phenotypes in Ino80-ablated mice with different genetic backgrounds will increase our understanding of how INO80 impacts tumorigenesis." (PMID 29383140, 2017). "Ino80 is downregulated in BAP1-defective cancer cells due to destabilization, suggesting a molecular basis for the BAP1 tumor-suppressor function." (PMID 27750218, 2016). "Mutations in INO80 subunits are not abundant in human cancers; however, several INO80 subunits have been found overexpressed." (PMID 36672401, 2023). "INO80 complex subunits exhibit a high frequency of alteration in multiple cancer types." (PMID 38020889, 2023). "Ultimately, INO80-mediated R-loop resolution supports DNA replication and transcription, fostering proliferation and safeguarding against DNA-damage-induced cell death in cancer cells." (PMID 37894353, 2023). "Furthermore, a high expression of INO80 was frequently found in cancer cell lines and tumor tissues, including in lung cancer, colon cancer, and melanoma." (PMID 36361605, 2022). "Interestingly, INO80 counteracts R-loops, promoting DNA replication in the presence of transcription, enabling proliferation in cancers." (PMID 34070411, 2021). "Whether resolution of R-loops by INO80 regulates oncogenic transcription and enables coordination of dysregulated gene expression with DNA replication in cancer cells is an exciting possibility." (PMID 32913330, 2020). "In conclusion, by identifying INO80 as a molecular link between cellular proliferation and silencing of R-loops, our study provides insight into how cancer cells balance transcription with replication, enabling unlimited growth in the presence of inherent replication stress conditions." (PMID 32913330, 2020). "DNA repair pathways, such as those involving RAD52 and INO80, are evolutionarily conserved, involved in genome instability and tumorigenesis, and predictive of therapeutic response in some cancers, thus representing potential tumor-specific biomarkers for chemotherapeutic efficacy." (PMID 31660150, 2019). "The findings pointed to the tumor-promoting role of the INO80 complex in several cancers." (PMID 31769422, 2019). "Furthermore, comparative analysis reveals subunits of INO80 and mTORC1 have high co-occurrence of alterations in human cancers." (PMID 29462149, 2018). "INO80 dysfunction may perturb DNA synthesis, gene regulation and DNA repair, potentially leading to genome instability and the development of cancer." (PMID 27750218, 2016). "Also, enrichment of differentially expressed genes in multi-KEGG pathways including pathways in cancer was confirmed by KEGG pathway enrichment analysis, indicating the importance of the INO80 complex in cellular biological processes such as cancer pathway." (PMID 27535137, 2016). "In summary, given that INO80 complex performs an important function in maintaining the normal cell cycle and genome stability, it is necessary to investigate the functions of INO80 complex in tumorigenesis and cancer therapy in the future." (PMID 26340092, 2015). "The Ino80 complex is a highly conserved ATP-dependent chromatin remodeling complex, involved in transcription, replication, and DNA repair while Ino80 contributes to activation of super-enhancers in the context of cancer, a feature shared with Brd4 in the context of senescence." (PMID 38534794, 2024).
cancer (continued). "Upon knocking down the INO80 complex in different types of cancer cells, the proteins (or complexes) or transcription cofactors recruited by INO80 in the promoter region of the miR-371–373 gene cluster may have different effects on the expression level of miR-372–373." (PMID 37445863, 2023). "However, the role of INO80 in cancer cell proliferation remains largely elusive." (PMID 32913330, 2020). "Additionally, cancer patients frequently have alterations in both INO80 genes and TOR genes, suggesting that disruption of both these components may facilitate the metabolic aberrations that are a hallmark of many cancer cells." (PMID 29462149, 2018). "Indeed, we observed a high co-occurrence of alterations in subunits of hINO80 and mTORC1 in a wide range of human cancers, suggesting that abrogation of both INO80 and mTORC1 may lead to the metabolic dysregulation that contributes to carcinogenesis." (PMID 29462149, 2018). "In recent years, many studies have identified the genome atlas in the INO80 and SWR1 family locus in cancer patients." (PMID 36361605, 2022). "ACTL6A, CHD2, and ACTB had the highest pan‐cancer G‐score for amplification, whereas CHD5, SHPRH, INO80, and ACTR8 had the highest pan‐cancer G‐score for deletions." (PMID 35789070, 2022). "Furthermore, silencing of INO80 appears to have a similar effect to dysfunction of KRAS, MYC, PIK3CA, and ERRB2, inhibiting the migration and metastatic abilities of cancer cells." (PMID 38020889, 2023). "INO80 complex, a member of the ATP-dependent chromatin remodeler family, is involved in multiple functions related to cancer stem cells and cancer progression, through both canonical and non-canonical INO80 complexes that directly modulate chromatin architecture and gene expression." (PMID 38020889, 2023). "An unbiased survey of the functions of Ino80 silencing‐repressed genes by both gene ontology (GO) analysis and KEGG analysis identified significant enrichment in physiological processes related to cancer, extracellular matrix and focal adhesion, reinforcing the link between Ino80 and cell invasion." (PMID 33724648, 2021). "We therefore tested whether combined inhibition of APE1 and Rad52 sensitizes cancer cells lacking INO80 or RNase H1 to death." (PMID 32913330, 2020). "In addition, a high co-occurrence of alterations in subunits of INO80 and mTORC1 was observed in PDAC and other cancers, suggesting that disruption of these pathways might contribute to the metabolic dysregulation involved in tumorigenesis." (PMID 31769422, 2019).
tumor (16 papers, 2016 to 2025). "In terms of anti-tumor immunity, INO80 has been found to cause T cell exhaustion, with its perturbation improving T cell persistence in tumors." (PMID 40541951, 2025). "In agreement with a potential role of chromatin remodeling in the prevention TRC-dependent DNA damage, SMARCA4-, SMARCA5- and INO80-deficient tumor samples display significantly increased R-loop mutation burden." (PMID 37898641, 2023). "A recent study demonstrates that Ino80 interacts with BRCA1-associated protein-1 (BAP1), a tumor suppressor that also stabilizes Ino80, in normal DNA replication." (PMID 27750218, 2016). "In agreement with previous reports, loss of INO80 significantly inhibited tumor growth." (PMID 29327641, 2017). "Similar to ARNTL, INO80 expression was significantly decreased in primary EC tumor cell lines (HEC-1A and RL95-2), but higher in metastatic EC cell lines (AN3CA and EFE-184)." (PMID 40541951, 2025). "It therefore appears that INO80 influences tumorigenesis via different mechanisms depending on the tumor type and genetic context." (PMID 29383140, 2017). "Although these functions suggest that INO80 acts as a tumor suppressor, its specific role in tumorigenesis has remained obscure." (PMID 29383140, 2017). "The finding that INO80 suppresses genomic instability led us to predict that INO80 would function as a tumor suppressor." (PMID 29383140, 2017). "Stable Ino80 knockdown or control HeLa and SiHa cells were subcutaneously injected into female nude mice and tumor growth was measured." (PMID 27750218, 2016). "To investigate whether INO80 participates in the tumor-promoting role of ARNTL in EC, we introduced Vector-ARNTL in the ARNTL-KO EC cells, and the successful exogenous overexpression of INO80 in cells was determined by RT-qPCR." (PMID 40541951, 2025). "Human INO80 chromatin remodeling complex (INO80 complex) as a transcription cofactor is widely involved in gene transcription regulation and is frequently highly expressed in tumor cells." (PMID 37445863, 2023). "Conversely, the noncanonical class of the INO80 complex is linked to a repressive histone modification, H3K27me3, suggesting that the INO80 complex can act as a tumor suppressor." (PMID 38020889, 2023). "A similar magnitude of tumor inhibition was observed in the colons in the Ino80+/−Apcmin/+ mice." (PMID 29383140, 2017). "Because there is a causal association between genomic instability and tumorigenesis, these findings suggest that INO80 may function as a tumor suppressor." (PMID 29383140, 2017). "Ino80 knockdown group tumor volumes and weights were reduced compared to controls." (PMID 27750218, 2016). "INO80 loss in our mouse model failed to cause tumor formation." (PMID 38020889, 2023). "Thus, haploinsufficiency in Ino80 has an impact on both tumor number and tumor size." (PMID 29383140, 2017). "Here, we used an epigenetics-focused CRISPR interference screen and identified ACTR5 (actin-related protein 5), a component of the INO80 chromatin remodeling complex, to be essential for HCC tumor progression." (PMID 36563143, 2022). "PTCSC3 is the tumor suppressor lncRNA of TC and negatively regulates STAT3/INO80 to attenuate the resistance to doxorubicin that favors prognosis." (PMID 35915656, 2022). "After INO80 was artificially upregulated in the ARNTL-KO AN3CA cells, tail vein injection of these cells led to an increased mortality rate of the huHSC-NOG-EXL mice and increased tumor metastasis burden in their lung tissues." (PMID 40541951, 2025).
infection (4 papers, 2013 to 2025). The state of being infected such as from the introduction of a foreign agent such as serum, vaccine, antigenic substance or organism. "To understand how INO80 regulates trophoblast migration and invasion at the molecular level, we carried out RNA high‐throughput sequencing (RNA‐seq) upon Ino80 silencing in HTR‐8/SVneo 3 days post‐infection." (PMID 33724648, 2021). "Other epigenetic modulators like DNA demethylases TET2 and TET3, histone variant genes, INO80 complex, PRC2 complex genes, EED and SUZ12 were also associated with DNA methylation changes upon infection." (PMID 27112593, 2016). "ICP4 binds promiscuously to host chromatin early in infection, and recruits both the transcriptional machinery and chromatin remodelers including the ATPase subunits of the SWI/SNF, INO80, and NuRD complexes." (PMID 40667204, 2025). "Ino80 components are found to higher extents later in infection (6 and 12 hpi) when viral DNA is replicating, and not in cases where DNA replication is less abundant such as early in infection or in n208 infected cells." (PMID 24147125, 2013).
blood cancer (1 paper, 2023). "As another example, module #46, consisting of the INO80 chromatin remodeling complex, is required for the survival of blood cancer cell lines with histone hyperacetylation." (PMID 37460547, 2023).
INO80 also shares sentences with these, for which no sentence is quoted: liver cancer (2 papers); sarcoma (2); breast tumors (1); diabetes (1); endothelial dysfunction (1); heart disease (1); Hypertension (1); Immunodeficiency (1); insomnia (1); Intellectual disability (1); lung carcinoma (1); malaria (1); neuroblastoma (1); neurodevelopmental disorder (1); pancreatic ductal adenocarcinoma (1); prostate tumor (1); Sepsis (1); small intestinal tumors (1).